RN7SKP94 (RN7SK pseudogene 94)
Gene: Miscellaneous RNA gene on chromosome 17 (57,789,449 to 57,789,732, forward strand). Ensembl gene ENSG00000222976.
Homologues: Orthologues: chimpanzee 7SK (95% identical). Paralogues in human: 7SK (79% identical), RN7SKP255 (78% identical), RN7SKP79 (77% identical), RN7SKP176 (76% identical), RN7SKP78 (76% identical), RN7SKP9 (76% identical), RN7SKP180 (76% identical), RN7SKP95 (76% identical), RN7SKP211 (76% identical), RN7SKP217 (76% identical), RN7SKP71 (76% identical), RN7SKP204 (75% identical), and 284 more.